PSD4 (pleckstrin and Sec7 domain containing 4)
Description:
Guanine nucleotide exchange factor for ARF6 and ARL14/ARF7. Through ARL14 activation, controls the movement of MHC class II-containing vesicles along the actin cytoskeleton in dendritic cells. Involved in membrane recycling. Interacts with several phosphatidylinositol phosphate species, including phosphatidylinositol 3,4-bisphosphate, phosphatidylinositol 3,5-bisphosphate and phosphatidylinositol 4,5-bisphosphate.
Synonyms: EFA6B; TIC
Tractability: Antibody: UniProt places it where antibodies can reach, with high confidence; its Gene Ontology location is reachable by antibodies, with medium confidence. PROTAC: ubiquitination databases record sites on it; its protein half-life has been measured.
Gene: Protein-coding gene on chromosome 2 (113,157,325 to 113,209,396, forward strand). Ensembl gene ENSG00000125637.
Subcellular location: Cell membrane; Cell projection, ruffle membrane
Gene Ontology:
Molecular function: guanyl-nucleotide exchange factor activity; phospholipid binding
Biological process: regulation of ARF protein signal transduction
Cellular component: cleavage furrow; membrane; plasma membrane; ruffle membrane
Genetic constraint (gnomAD): Loss-of-function variants: 58 observed, 110.07 expected, observed/expected ratio (o/e) 0.53, 90% interval 0.43 to 0.66. The upper end of that interval is the gene's LOEUF score, 0.66, which puts it in group 2 of 6, group 1 being the genes least tolerant of losing a copy. Missense variants: 1,254 observed, 1,337.6 expected, observed/expected ratio (o/e) 0.94, 90% interval 0.89 to 0.98. Synonymous variants: 526 observed, 534.41 expected, observed/expected ratio (o/e) 0.98, 90% interval 0.92 to 1.06.
Homologues: Orthologues: chimpanzee PSD4 (99% identical), macaque PSD4 (92% identical), rabbit PSD4 (73% identical), guinea pig PSD4 (70% identical), rat Psd4 (67% identical), mouse Psd4 (67% identical), dog PSD4 (58% identical), Drosophila melanogaster siz (11% identical), Drosophila melanogaster garz (10% identical), Drosophila melanogaster Sec71 (10% identical), Caenorhabditis elegans mon-2 (10% identical), Caenorhabditis elegans gbf-1 (10% identical), and 1 more. Paralogues in human: PSD (29% identical), PSD3 (26% identical), PSD2 (26% identical), IQSEC1 (14% identical), IQSEC2 (14% identical), IQSEC3 (14% identical), MON2 (13% identical), GBF1 (12% identical), ARFGEF2 (11% identical), ARFGEF1 (11% identical), CYTH1 (9% identical), CYTH2 (9% identical), and 3 more.
Diseases named in the same sentence as PSD4 in open-access papers:
PSD4 is named in the same sentence as 14 diseases in open-access papers, as found by Europe PMC text mining. Sharing a sentence is not in itself a finding about the gene and the disease. The quoted sentences say what the papers report.
breast cancer (6 papers, 2014 to 2022). A primary or metastatic malignant neoplasm involving the breast. "Another signature gene, ALG3, has a higher expression in samples of breast cancer with advanced stages than those with early stages and the decreased expression of PSD4 (EFA6B) was associated with poor prognosis of patients with breast cancer." (PMID 31355144, 2019).
hepatocellular carcinoma (4 papers, 2021 to 2025). A malignant tumor that arises from hepatocytes. "In hepatocellular carcinoma (HCC), type I collagen promotes cancer cell stemness and metastasis through the CD44/DDR1/YAP axis and the PSD4/ARF6 signaling pathway, respectively." (PMID 40563472, 2025). "Our results reveal that the DDR1/PSD4/ARF6 signaling axis acts as an important inducer in the regulation of the migration, invasion and lung metastasis of hepatocellular carcinoma cells by collagen induced DDR1 signaling." (PMID 35140331, 2022).
Stroke (2 papers, 2021 to 2024). Sudden impairment of blood flow to a part of the brain due to occlusion or rupture of an artery to the brain. "Stroke-injured mice displayed a significant motor deficit on the grid walking task at PSD4 prior to treatment with Cre or Neurod1 (p = 0.003, p = 0.002, respectively)." (PMID 38540276, 2024). "CNEPs were transplanted into the stroke lesion of immunocompromised SCID-Beige mice on PSD4 (acute phase) following an ET-1 induced stroke in the motor cortex." (PMID 33994947, 2021). "On PSD4, one cohort of mice (Stroke + cNEP) received 1 × 105 cNEP cells into the stroke injury site." (PMID 33994947, 2021). "Cortical lesion volumes were not different between PSD4 and PSD40 in Stroke + cNEP transplanted mice." (PMID 33994947, 2021).
alcohol (1 paper, 2021). "This evidence indicates that PSD4 is specifically downregulated in alcohol‐related HCC and may play a role in improving HCC patient survival." (PMID 33932127, 2021). "Here, using R‐based bioinformatics analysis, we identify the ARF GTPase GEF PSD4 (EFA6B) as a hypermethylated, suppressed gene in alcohol‐related HCC tumors." (PMID 33932127, 2021).
breast tumors (1 paper, 2020). "In human breast tumors, the reduced expression of PSD4 was associated with increasing the poor prognosis and cancer stemness." (PMID 32640634, 2020).
metastatic tumors (1 paper, 2021). "Here, to determine the mechanism by which the loss of EFA6B might facilitate the progression of metastatic tumors, we analyzed the consequence of knocking out its gene (PSD4) in normal human mammary cells." (PMID 33850160, 2021).
tumor (6 papers, 2017 to 2022). "We found a significant reduction of PSD4 expression in the metastatic samples, further corroborating the role of EFA6B loss in tumor invasion." (PMID 33850160, 2021). "PSD4 downregulation was associated (Fisher’s exact test) with younger patients’ age, higher pathological grade and tumor size, ductal type, and higher frequency of TN subtype (p < 0.001), and shorter disease-free survival (DFS)." (PMID 33850160, 2021). "Combined with clinicopathological analysis of patients with HCC, high expression of PSD4 was associated with poor tumor differentiation (P = 0.031), incomplete tumor encapsulation (P = 0.001), advanced tumor TNM stage (P = 0.001), and tumor recurrence (P = 0.001)." (PMID 35140331, 2022). "We also demonstrate that PSD4 functions as tumor suppressor in HCC cells via negatively modulating pro‐EMT CDC42 activity." (PMID 33932127, 2021). "Hepatocyte‐specific PSD4 overexpression reduced ethanol/DEN‐induced HCC tumor progression and EMT marker expression in vivo." (PMID 33932127, 2021). "To investigate whether hepatocyte‐specific PSD4 overexpression has an impact on alcohol‐induced HCC tumor progression, we utilized a previously reported murine model of ethanol/DEN‐induced HCC." (PMID 33932127, 2021). "Consistent with our in vitro findings, PSD4 suppressed ethanol/DEN‐induced HCC progression along with reducing cadherin switching and vimentin expression in HCC tumor cells in vivo." (PMID 33932127, 2021). "Functionally, PSD4 inhibited HCC cells proliferation, migration, and invasiveness in vitro and suppressed alcohol‐induced HCC tumor progression in vivo." (PMID 33932127, 2021). "There have been no genomic studies showing PSD4/EFA6B to be a tumor suppressor gene, and our orthotopic xenograft experiments with MCF10A WT or EFA6BKO cells injected into immunosuppressed mice did not produce any tumor arguing that the loss of EFA6B alone is not a driver mutation." (PMID 33850160, 2021).
cancer (2 papers, 2020 to 2021). A tumor composed of atypical neoplastic, often pleomorphic cells that invade other tissues. "We also compared the PSD4 mRNA expression in metastatic samples versus the paired primary BC by taking advantage of a publicly available series of 29 matched metastasis/primary cancer pairs." (PMID 33850160, 2021). "In the grade 3 carcinoma, PSD4 and GSN had the higher betweenness (BC = 1.0; BC = 0.193548)." (PMID 32640634, 2020).
PSD4 also shares sentences with these, for which no sentence is quoted: invasive breast carcinoma (2 papers); glioma (1); invasive ductal carcinoma (1); ovarian carcinoma (1); plague (1); renal carcinoma (1).